KLRC1 (killer cell lectin like receptor C1)
Diseases named in the same sentence as KLRC1 in open-access papers (continued):
Sharing a sentence is not in itself a finding about the gene and the disease.
tumor (continued). "Expression of KLRC1 gene, which encodes NKG2A, was found to correlate with HLA-E in tumor samples." (PMID 33671917, 2021). "In addition, we found that the expression of KLRC1 is negatively correlated with tumor purity in 32 tumor types and positively correlated with CD8+ T-cell infiltration levels in 34 tumor types." (PMID 32010126, 2019). "Furthermore, several tumor suppressor genes along with the KLRC1 (a member of natural killer receptor) were also down-regulated in the peritumoral brain tissue." (PMID 23472076, 2013). "Interestingly, expression of NKG2A, the inhibitory receptor encoded by Klrc1, showed a biphasic expression pattern, largely independent of time within the tumor." (PMID 38267402, 2024). "KLRC1 and SIGLEC5 mediate immune activation and suppression, respectively, and are involved in tumor immune surveillance." (PMID 41438620, 2025). "These genes include three tumour suppressors (DMBT1, MTUS1, and KLRC1), two genes involved with cell communication and myelin (GJB1 and KLK6), and a P450 monooxygenase involved in the synthesis of cholesterol and lipids (CYP4F12)." (PMID 37628980, 2023). "We also noted that the tumor enriched C5 cells were characterized by the expression of resting NK cells markers, such as AREG, XCL1, and KLRC1, while the C9 cells, which expressed the CX3CR1 and NKG7, were abundant in normal tissues." (PMID 36008393, 2022). "We also investigated NK inhibitory receptors: KLRC1 (NKG2A) and KLRD1 (CD94) that suppressed NK cell anti-tumor activity via binding HLA-E30 to evaluate differential NK cell-mediated effects in KIRP and SKCM." (PMID 32533054, 2020). "One major class of genes controlling both activating and inhibitory NK cell receptor groups (NKGs) is Klrc1 [NKG2A], Klrc2 [NKG2C], and Klrk1 [NKG2D] and are involved in specific interactions with the MHC of tumor cells and virally infected cells." (PMID 31009335, 2019). "Increased expression of KLRC1, CCL5, PLP1, CD163, MSR1, and GPNMB was found following treatment and tumor recurrence." (PMID 30151353, 2018). "KLRC1 and CCL5 have been shown to be involved in compromising anti-tumoral responses with KLRC1 inhibiting the killing ability of CD8+ T cells and CCL5 recruiting immunosuppressive T regulatory cells into the tumor microenvironment." (PMID 30151353, 2018). "Several tumour suppressor genes (BAI3, PEG3, PRDM2, RB1CC1) along with the natural killer receptor KLRC1 were also down regulated in BAT." (PMID 23472076, 2013). "As a subtype of immunosuppressive NK cells, we observed a high level of TGF-β signaling in KLRC1+ NK cells, suggesting its negative impact on anti-tumor immunity, particularly on CD8+ T cells." (PMID 38169544, 2024). "The presence of CD8+ T cells expressing inhibitory markers such as LAG3, TIGIT, KLRC1, and PD-1, and FOXP3+ regulatory CD4+ T cells may prevent effective T cell–mediated tumor control in PDAC." (PMID 37751306, 2023). "Correlative elaboration of key molecules including FCER1G, ZGMM, KIR2DL4, KIR3DH5, KLRC1, KLRB1, and FKBP5 among the 5 cell‐type clusters in evolutionary development trajectory of NKT for immune escalation against evasion of vital tumor cells and mutants was further illustrated by Violin plots." (PMID 37693048, 2023). "The study went on to show that, among the four g1 ILC clusters, the one most enriched in the tumor also displayed the highest expression of inhibitory receptors/exhaustion markers, such as KLRC1 (NKG2A) and LAG3, mirroring the phenotype of murine intILC1 in cancer." (PMID 36372017, 2022). "Interestingly, KLRC1 has recently been shown to function as a checkpoint inhibitor that when blocked can promote NK cell and CD8+ T cell-mediated anti-tumor immunity." (PMID 34539622, 2021). "After that, we selected LUAD and LUSC, in which the expression level of KLRC1 has an obviously negative correlation with tumor purity in TIMER." (PMID 32010126, 2019).
tumor (continued). "Further, Klrc1, an NK cell marker, were decreased in the draining lymph nodes and spleens of Stat4−/− mice with lung metastases, indicating diminished anti-tumor response by cytotoxic lymphocytes." (PMID 32010142, 2019). "Similarly, the KLRC1 expression level had negative correlation with tumor purity and positive correlation with infiltrating levels of B cell, CD8+ T cell, CD4+ T cell, Macrophage, Neutrophil and Dendritic cell." (PMID 34368124, 2021).
cancer (162 papers, 2007 to 2026). A tumor composed of atypical neoplastic, often pleomorphic cells that invade other tissues. "Anti‐KLRC1 (NKG2A) monoclonal antibody (Monalizumab) has been proposed as a novel checkpoint inhibitor used in clinical trials to treat several carcinomas." (PMID 35184420, 2022). "A previous study found KLRC1 expression changed with CD8+ T cell infiltration in 34 types of human cancers." (PMID 34368124, 2021). "We additionally identified as positive biomarkers several interactions between MHC-I genes and the corresponding receptors (HLA-B_HLA-E → KLRD1 and HLA-E → KLRC1 in 17 and 14 cancer types, respectively)." (PMID 34430923, 2021). "We assessed the connection between KLRC1 expression and immune infiltration levels in 39 types of cancer through the TIMER database." (PMID 32010126, 2019). "Among the subsets of lymphocytes, the KLRC1 expression especially correlated with the CD8+ T-cell infiltration level in 34 types of human cancer." (PMID 32010126, 2019). "To evaluate KLRC1 expression in human cancers, we used the RNA-seq data of multiple malignancies in TCGA to examine the expression level of KLRC1." (PMID 32010126, 2019). "Then, we investigated whether there was a correlation between KLRC1 expression and the immune infiltration levels in different types of cancers." (PMID 32010126, 2019). "Moreover, KLRC1 expression has positive correlations with infiltrating levels of B cells in 23 cancer types, CD4+ T cells in 20 cancer types, macrophages in 17 cancer types, neutrophils in 31 cancer types, and dendritic cells in 32 cancer types." (PMID 32010126, 2019). "Meanwhile, the highly expression of HLA-E as a ligand for KLRC1, KLRK1, and NKG2A/CD94 on the surface of NK cells can help cancer cells evade immune killing by NK cells." (PMID 39583114, 2024). "Taking these factors into account, we developed a CRISPR-based gene knockout method to target A2AR, CBLB, CD96, and KLRC1 (NKG2A) genes to evaluate their antitherapeutic role in AML and B-ALL cancer." (PMID 38003255, 2023).
infection (67 papers, 2010 to 2025). The state of being infected such as from the introduction of a foreign agent such as serum, vaccine, antigenic substance or organism. "The M2 infection module revealed Chil3, Il4, Cx3cr1, Emr1 and Ccl2 as hubs, while module M6, associated with vaccination, disclosed Prf1, Klrc1, IFN-γ, Ncr1 and Tbx21 as hub proteins." (PMID 39563428, 2024). "In contrast, 43 genes associated with innate immune cells were down-regulated following YFV-DakH1279 infection and only three genes were upregulated (KLRC1, CPA3 and RSAD2)." (PMID 25412185, 2014).
KLRC1 also shares sentences with these, for which no sentence is quoted: viral infections (35 papers); leukemia (20); acute myeloid leukemia (15); HCMV infection (13); autoimmune disease (11); breast carcinoma (11); colorectal cancer (11); chronic lymphocytic leukemia (10); head and neck squamous cell carcinoma (10); hepatocellular carcinoma (10); HIV-1 infection (10); cervical carcinoma (9); ovarian carcinoma (9); rheumatoid arthritis (8); non-small cell lung carcinoma (7); pancreatic cancer (6); celiac disease (5); colitis (5); infectious disease (5); influenza (5); systemic lupus erythematosus (5); B-cell lymphoma (4); chronic graft versus host disease (4); chronic hepatitis B (4); colon carcinoma (4); hematologic malignancies (4); infectious mononucleosis (4); liver cancer (4); acute lymphoblastic leukemia (3); adenocarcinoma (3).
A further 101 diseases each share a sentence with KLRC1 in 3 papers or fewer.